CALHM5 (calcium homeostasis modulator family member 5)
Description:
May assemble to form large pore channels with gating and ion conductance likely regulated by membrane lipids.
Synonyms: C6orf188; FAM26E; dJ493F7.3; MGC45451
Tractability: Small molecule: a structure with a bound ligand is known. Antibody: UniProt predicts a signal peptide or a membrane-spanning region; its Gene Ontology location is reachable by antibodies, with medium confidence. PROTAC: ubiquitination databases record sites on it.
Gene: Protein-coding gene on chromosome 6 (116,511,639 to 116,524,788, forward strand). Ensembl gene ENSG00000178033.
Subcellular location: Membrane
Subcellular location (Human Protein Atlas): Golgi apparatus
Gene Ontology:
Molecular function: monoatomic ion channel activity; protein binding; monoatomic cation channel activity
Biological process: calcium ion homeostasis; ATP export; monoatomic cation transmembrane transport; monoatomic ion transmembrane transport; regulation of artery smooth muscle contraction
Cellular component: plasma membrane; membrane
Genetic constraint (gnomAD): Loss-of-function variants: 18 observed, 23.62 expected, observed/expected ratio (o/e) 0.76, 90% interval 0.53 to 1.13. The upper end of that interval is the gene's LOEUF score, 1.13, which puts it in group 4 of 6, group 1 being the genes least tolerant of losing a copy. Missense variants: 360 observed, 382.95 expected, observed/expected ratio (o/e) 0.94, 90% interval 0.86 to 1.03. Synonymous variants: 148 observed, 148.98 expected, observed/expected ratio (o/e) 0.99, 90% interval 0.87 to 1.14.
Homologues: Orthologues: chimpanzee CALHM5 (99% identical), macaque CALHM5 (97% identical), dog CALHM5 (90% identical), rabbit CALHM5 (90% identical), pig CALHM5 (88% identical), guinea pig CALHM5 (86% identical), rat Calhm5 (85% identical), mouse Calhm5 (83% identical), zebrafish calhm5.1 (50% identical), zebrafish calhm5.2 (50% identical), tropical clawed frog calhm5 (50% identical), Caenorhabditis elegans clhm-1 (23% identical). Paralogues in human: CALHM6 (37% identical), CALHM2 (28% identical), CALHM4 (27% identical), CALHM3 (20% identical), CALHM1 (19% identical).
Diseases named in the same sentence as CALHM5 in open-access papers:
CALHM5 is named in the same sentence as 2 diseases in open-access papers, as found by Europe PMC text mining. Sharing a sentence is not in itself a finding about the gene and the disease. The quoted sentences say what the papers report.
cancer (1 paper, 2023). A tumor composed of atypical neoplastic, often pleomorphic cells that invade other tissues. "Further, AIWrap identified six new genes (VCX3A, CALHM5, ZMYND10, FOXE1, PLAT, FADD) which could be related to smoking in cancer patients, thus providing an opportunity for identifying previously unknown biological functions." (PMID 37853338, 2023).
CALHM5 also shares sentences with these, for which no sentence is quoted: breast carcinoma (1 paper).